CRP (C-reactive protein)
Diseases named in the same sentence as CRP in open-access papers (continued):
Sharing a sentence is not in itself a finding about the gene and the disease.
breast cancer (continued). "There might be a reduced inflammatory process via a reduction in TNF-α, IL-6, IL-18, and CRP expression in breast cancer mice that were subjected to moderate intensity exercise." (PMID 32309219, 2020). "We hypothesized that breast cancer patients with elevated CRP levels would be more likely to report pain, which may identify CRP as an inflammatory biomarker for pain." (PMID 31138314, 2019). "Our results provide new evidence in this regard, since not having received hormone therapy may be a predictor of a greater reduction in CRP concentration in female survivors of breast cancer." (PMID 31414667, 2019). "A large body of evidence indicates that circulating inflammatory biomarkers, including interleukin (IL)-4, IL-6, IL-8, C-reactive protein (CRP), and tumor necrosis factor-α (TNF-α), may be associated with breast cancer risk." (PMID 31430979, 2019). "Path analysis revealed that the serum CRP level, but not the serum IL-6 level, mediated the association between dietary magnesium intake and breast cancer risk." (PMID 30962499, 2019). "Systemic inflammatory markers such as C-reactive protein (CRP), fibrinogen, ferritin, albumin, transferrin, and blood leukocyte components like neutrophils and lymphocytes are associated with prognosis of RCC, colorectal, and breast cancers." (PMID 29541572, 2018). "Moreover, CRP genetic polymorphism was associated with lymph node (LN) metastasis in several cancer types, including ESCC, NSCLC, and breast cancer." (PMID 29568406, 2018). "C-reactive protein (CRP), an acute-phase protein of hepatic origin that is a sensitive yet nonspecific marker of the inflammatory response, has been associated with breast cancer risk in some but not all studies." (PMID 28983080, 2017). "We carried out a case-control study to prospectively assess whether pre-diagnostic levels of CRP, TNF-α, IL-6, leptin, and adiponectin in plasma are associated with risk of developing breast cancer." (PMID 28983080, 2017). "The lack of association between CRP and breast cancer risk in premenopausal women suggests that inflammation plays little or no role in premenopausal breast cancer." (PMID 28983080, 2017). "Most recently, higher circulating CRP levels were associated with increased incidence of breast cancer among women not using hormone therapy among WHI participants." (PMID 27338371, 2016). "Among the 15 studies included, two showed an insignificant negative association between one unit change in ln(CRP) and breast cancer, and the other thirteen showed positive association, four of which showed statistical significance." (PMID 26001129, 2015). "Elevated CRP levels significantly increased the risk of postmenopausal breast cancer (OR = 1.08, 95% CI: 1.00-1.16), but not significantly for premenopausal breast cancer (OR = 1.08, 95% CI: 0.91-1.28)." (PMID 26001129, 2015). "The addition of CRP lowering agents along with chemotherapeutic drugs may improve the survival of breast cancer patients." (PMID 26693355, 2015). "The exact role of CRP in the pathogenesis of carcinogenesis is uncertain, but evidence from numerous prospective and case-control studies has supported a role of CRP in different aspects of breast cancer." (PMID 26693355, 2015). "Elevated CRP levels significantly increased a risk of breast cancer among postmenopausal women (OR = 1.08, 95% CI: 1.00–1.16) but not in premenopausal breast cancer (OR = 1.08, 95% CI: 0.91–1.28)." (PMID 26693355, 2015). "The combined OR per natural log unit change in CRP for breast cancer was 1.16 (95% CI: 1.06-1.27)." (PMID 26001129, 2015). "Thereinto, a meta-analysis published in 2009 found that a natural log (ln) unit increase in CRP was not statistically significant associated with breast cancer risk (relative risk [RR] = 1.10, 95% confidence interval [CI]: 0.97–1.26)." (PMID 26001129, 2015). "We saw in this study, hs-CRP level in breast cancer group was notable." (PMID 26865928, 2015).
breast cancer (continued). "Further studies, especially with high-quality and more breast cancer cases involved cohort studies, are needed to identify whether CRP, as a marker of inflammation, does play a direct role in breast carcinogenesis." (PMID 26001129, 2015). "Wang and Sun in their systematic review reported no strong evidence between CRP levels and risk of breast cancer." (PMID 26693355, 2015). "Among premenopausal women, the CT and TT genotypes of CRP-rs1205 were associated with decreased breast cancer risk in EA, but not AA women." (PMID 23991131, 2013). "Serum ferritin and CRP levels in HER2/neu-overexpressing breast cancer patients (n = 66)." (PMID 23300545, 2012). "Therefore, both of the inflammatory biomarkers serum ferritin and CRP have strong prognostic and predictive value in advanced breast cancer patients receiving trastuzumab-containing therapy." (PMID 23300545, 2012). "Our data suggest that use of NSAIDs may be one way to control circulating levels of CRP/SAA in breast cancer survivors." (PMID 22873489, 2012). "Elevated CRP levels across tertiles at the time of diagnosis were associated with reduced overall and disease-free survival and with increased risk of death from breast cancer (log-rank trend for all, P < 0.001), but not with recurrence." (PMID 21639875, 2011). "The largest study so far which comprised approximately 700 women treated successfully for early stage breast cancer found that elevated levels of CRP measured two and a half years after the time of diagnosis were associated with reduced disease-free and overall survival." (PMID 21639875, 2011). "Third, host behaviour: plasma CRP levels may outline the general health of the woman at the time of diagnosis of breast cancer." (PMID 21639875, 2011). "Previous studies have shown that elevated C-reactive protein concentrations have prognostic value in patients with a variety of primary operable tumours and also in patients with advanced breast cancer." (PMID 17375036, 2007). "Additionally, multiple RCTs have suggested that changes in CRP and other inflammatory markers may be related to changes in body weight in breast cancer patients." (PMID 40895542, 2025). "CRP could be a positive‐regulator for hepcidin in breast cancer." (PMID 40791284, 2025). "Consistent with this hypothesis, CRP levels in this study were statistically increased in the recurrenced group compared to the non‐recurrenced, suggesting that CRP could potentially be a positive regulator of hepcidin in breast cancer patients." (PMID 40791284, 2025). "The incorporation of cardiovascular biomarkers (e.g., lipid profiles, C-reactive protein, blood pressure) and longitudinal follow-up to evaluate the sustained impact of Mediterranean diet adherence on cardiovascular outcomes in breast cancer survivors could be explored in future work." (PMID 40901290, 2025). "Elements of systemic inflammation, such as platelets, lymphocytes and high-sensitivity C-reactive protein (hs-CRP), and biochemical markers in the blood, such as C-reactive protein levels and albumin levels, are valuable prognostic indicators for cancer, including breast cancer." (PMID 40860681, 2025). "Additionally, two small randomized controlled trials looking at inflammatory markers in breast cancer survivors demonstrated that aerobic and resistance-based exercise programs reduced inflammatory markers, such as C-reactive protein (CRP) and tumor necrosis factor alpha (TNF-α), respectively." (PMID 41283543, 2025). "Finally, we only investigated the causal relationship between CRP, IL-1, IL-6 expression levels and breast cancer risk, without analyzing other biomarkers of chronic inflammation and transcription factors, which are also crucial for breast cancer occurrence." (PMID 38263420, 2024). "However, we also found an inverted U-shaped relationship between CRP and breast cancer." (PMID 38360584, 2024).
breast cancer (continued). "In the multi-state survival analysis, we further found that CRP was mainly associated with invasive breast cancer and the transition from cancer incidence to mortality, while testosterone and IGF-1 were more likely to impact the early state of breast cancer development." (PMID 38000092, 2023). "In addition to mammary cancer, elevated concentration of CRP was detected in hemangiosarcoma, nasal adenosarcoma, cholangiocellular carcinoma, acute lymphoblastic leukemia, malignant histiocytosis, lymphoma, malignant mesothelioma, and neuroendocrine carcinoma." (PMID 37009523, 2023). "As CRP is a biomarker that reflects the systemic burden of inflammation, our results suggest that chronic inflammation may play a more important role in breast cancer development and prognosis." (PMID 38000092, 2023). "Acute rise in inflammatory markers soluble tumor necrosis factor receptor II, interleukin 1 receptor antagonist and C-reactive protein was observed in a study of breast cancer survivors where authors implied these may remain elevated long into cancer survivorship." (PMID 37025582, 2023). "In summary, our study suggests that high levels of CRP, leptin and leptin-to-adiponectin ratio could lower breast cancer risk among premenopausal women but not among postmenopausal women." (PMID 35430795, 2022). "Particularly, we might expect to find an association between inflammatory biomarkers and breast cancer risk only among non-exogenous hormones users, similarly to what is observed for CRP in previous studies." (PMID 35430795, 2022). "Among the clinical trials assessing the efficacy of this antioxidant, a pilot study evaluated whether the combination of HT, omega-3 fatty acids, and curcumin would reduce CRP and musculoskeletal symptoms in breast cancer patients receiving adjuvant hormonal therapies." (PMID 33572626, 2021). "Thus, IL-6 and CRP may be involved in inflammatory pathways connected to breast cancer tumorigenesis." (PMID 33441805, 2021). "Also, genetically predicted CRP was strongly associated with increased risk for hormone-receptor positive or human epidermal growth factor receptor-2 negative breast cancer." (PMID 33614510, 2020). "In the future, large-scale prospective epidemiological studies are required to investigate whether the identified inflammation-related dietary factors affect circulating inflammatory markers, such as CRP, and circulating cytokine levels, and the development of breast cancer in Korean women." (PMID 31430979, 2019). "Therefore, determining dietary factors in relation to CRP and HbA1c may shed light on whether these dietary factors can influence comorbidities among women with breast cancer." (PMID 31443226, 2019). "However, CRP has not been associated with breast cancer risk in epidemiologic studies even though inflammation also plays an important role in breast cancer risk." (PMID 25132995, 2014). "In summary, pre-operatively elevated CRP levels at the time of diagnosis were associated with shorter DFS and OS independent of established prognostic factors in node-negative breast cancer, supporting a possible link between inflammation and prognosis in breast cancer." (PMID 25340395, 2014). "Since higher CRP and SAA levels adversely affect survival among breast cancer survivors, using a more precise measure of body fat (a predictor of CRP and SAA) may be useful for accurately identifying those women who could improve prognosis by decreasing body fat." (PMID 22873489, 2012). "The cumulative incidence of death from breast cancer among breast cancer patients increased with increasing levels of CRP (log-rank trend, P < 0.001) reaching 11%, 19%, and 20% among women in the lowest, middle, and highest tertile of CRP at the end of follow-up." (PMID 21639875, 2011).
breast cancer (continued). "Our findings of a positive association between elevated CRP levels and poor breast cancer prognosis are in contrast to negative studies with 110 to 300 patients, but are indirectly supported by findings from other studies with 85 to 734 patients which did report a positive association." (PMID 21639875, 2011). "Therefore, the prognostic value of C-reactive protein and albumin in patients with primary operable breast cancer remains unclear." (PMID 17375036, 2007). "For a number of tumor markers, such as CRP, CYFRA 21-1, ferritin, CA27.29, and CA19-9, a sharp increase in content was observed at advanced stages of breast cancer compared to the healthy control." (PMID 40699615, 2025). "In blood tests, apart from miRNA, an elevation in the concentrations of LDH, CRP, CA15‐3, CEA, CSCs, CTCs, cfDNA, copper ions or serum ferritin serves as an indication of a poor prognosis for canine mammary tumours." (PMID 40095734, 2025). "In the first subgroup, the marker levels in breast cancer will increase relative to the healthy control (EGFR2, CRP, CA-125, CEA, and CYFRA 21-1)." (PMID 40699615, 2025). "Taken together, this study indicates that CRP, CA15‐3, and MCV levels increase, while hemoglobin, RBC count, and serum iron decrease with advancement of breast cancer." (PMID 40791284, 2025). "This study also assessed the correlation between hepcidin levels and a commonly used breast cancer biomarker, the cancer antigen 15‐3 (CA15‐3), and one of the potential regulators of hepcidin in cancers, the C‐reactive protein (CRP)." (PMID 40791284, 2025). "When we added monocyte count, neutrophil count, and C-reactive protein to the fully adjusted models, the effect sizes of NWO on postmenopausal breast cancer were attenuated by 3.74%, 11.23%, and 19.25%, respectively." (PMID 39609539, 2025). "Neutrophil-to-lymphocyte ratio (NLR), lymphocyte-to-monocyte ratio (LMR), c-reactive protein (CRP), and systemic immune-inflammation index (SII) are some disease markers or models that have been shown to be able to predict the prognosis of breast cancer." (PMID 38169970, 2024). "An inverse U-shaped relationships between CRP, CAR and CLR, and breast cancer were also observed using cubic spline models (with p values for non-linearity of 0.0002, 0.0003, and 0.0035, respectively)." (PMID 38360584, 2024). "C-reactive protein (CRP), which is often used as a systemic marker of inflammation, is elevated in breast cancer patients treated with adjuvant chemotherapy in some but not all studies." (PMID 39415181, 2024). "In this study, we found that the levels of inflammation (CRP, CAR, and LCR) and IR (TyG, LHR, TG/HDL-c, and TC/HDL-c) in breast cancer patients with BMI ≥ 24 kg/m2 were significantly higher than those in patients with BMI < 24 kg/m2." (PMID 36922570, 2023). "Serum CRP, testosterone, and IGF-1 have different impacts on the transitions of different breast cancer states, confirming the role of chronic inflammation and endogenous hormones in breast cancer progression." (PMID 38000092, 2023). "CRP, testosterone, and IGF-1 were found to have different impacts on the transitions of different breast cancer states, confirming the role of chronic inflammation and endogenous hormones in breast cancer progression." (PMID 38000092, 2023). "Correlations observed between prognostic parameters and the serum biomarkers CA 15-3, CRP and LDH evaluated in canine mammary tumors (CMT)." (PMID 36938312, 2023). "Most existing studies on the effects of exercise on inflammatory factors and IGF systems in breast cancer survivors examine IL-6, IL-10, IL-1β, TNF-α, CRP, IGF-1, and IGFBP-3 levels." (PMID 36482346, 2022). "Recently, palbociclib treatment ameliorated the clinical symptoms and decreased serum levels of CRP and MMP-3 in patients with advanced breast cancer and RA." (PMID 34849618, 2022).
breast cancer (continued). "Insufficient sleep leads to increased concentrations of inflammatory markers, such as C-reactive protein (CRP), while inflammation is thought to be related to the incidence of breast cancer and lung tumors." (PMID 35565879, 2022). "Papila and colleagues compared serum values of NF-ƙB, PTX-3, IL-6, CRP, TNF-α, and sTRAIL (soluble TNF-related apoptosis-inducing ligand) and PCT (procalcitonin) in 40 individuals diagnosed with breast cancer, 40 with colon cancer, and 30 health controls." (PMID 36499628, 2022). "The measurement of high-sensitivity C-reactive protein (hs-CRP) using a high-sensitivity (hs) assay had a predicted impaired LVEF with 92.9% sensitivity and 45.7% specificity in breast cancer patients." (PMID 34711013, 2021). "A clinical trial has demonstrated that San Huang decoction remarkably reduced the volume of exudate after breast cancer surgery and the expression of TNF-α, IL-6, IL-8 and C-reactive protein (CRP) to improve the inflammation." (PMID 34722304, 2021). "They reported that metformin decreased insulin, glucose, leptin, C-reactive protein (CRP), HOMA-IR, and Ki-67 levels, which attenuated the outcome in breast cancer patients." (PMID 33917520, 2021). "As key inflammatory biomarkers C-reactive protein (CRP) and interleukin-6 (IL6) play an important role in the pathogenesis of non-inflammatory diseases, including specific cancers, such as breast cancer (BC)." (PMID 34572592, 2021). "In order to investigate how exercise in breast cancer affects inflammatory cytokines, IL-6, IL-18, TNF-α, and CRP mRNA expression levels were analyzed in the livers of the study mice." (PMID 32309219, 2020). "This study examined an inflammatory biomarker, C-reactive protein (CRP), in RT-related pain in breast cancer." (PMID 31138314, 2019). "We analyzed data collected from 3042 breast cancer survivors enrolled in the Women’s Healthy Eating and Living (WHEL) Study who had provided detailed dietary intakes and measurements of plasma C-reactive protein (CRP) and hemoglobin A1c (HbA1c)." (PMID 31443226, 2019). "The measurement of C-reactive protein (CRP) is a marker of general health, longevity, frailty, and overall breast cancer survival." (PMID 31443226, 2019). "Still, we have not analyzed inflammation-based prognostic scores, especially the ones that use C-reactive protein such as modified Glasgow prognostic score, to draw a conclusion that PLR is the best single prognostic parameter in breast cancer." (PMID 30048474, 2018). "Our results suggest that the preoperative CRP and PLR values significantly affect DFS in patients with breast carcinoma, and are superior to the NLR and LMR in terms of prognostic reliability." (PMID 28489884, 2017). "We investigated the association between serum inflammatory markers (C-reactive protein (CRP), absolute granulocyte count (AGC) and granulocyte-to-lymphocyte (G/L) ratio) and breast cancer (BCa) mortality in American women while accounting for adiposity." (PMID 27294662, 2016). "This is in contrast other studies in breast cancer survivors who reported correlations between physical activity and several metabolic variables including fasting insulin, HOMA-IR, CRP, leptin, IGF-I and IGFBP-3." (PMID 23855321, 2013). "The present findings, therefore, confirm that inflammatory markers, specifically CRP and TNF-α are elevated in newly diagnosed patients with breast cancer." (PMID 23374911, 2013). "We examined the prostate antigen PSA, the breast cancer markers CA 27.29 and CA15-3, the ovarian cancer marker CA 125, the general cancer marker CEA, and the inflammation marker C – reactive protein." (PMID 23947403, 2013). "C-reactive protein (CRP) and Serum amyloid A protein (SAA) increases with systemic inflammation and are related to worse survival for breast cancer survivors." (PMID 22873489, 2012).